PPP2R3C (protein phosphatase 2 regulatory subunit B''gamma)
Description:
May regulate MCM3AP phosphorylation through phosphatase recruitment (By similarity). May act as a negative regulator of ABCB1 expression and function through the dephosphorylation of ABCB1 by TFPI2/PPP2R3C complex. May play a role in the activation-induced cell death of B-cells (By similarity).
Synonyms: C14orf10; G5PR; FLJ20644; G4-1; GDRM; MEGD; SPGF36
Tractability: PROTAC: ubiquitination databases record sites on it.
Gene: Protein-coding gene on chromosome 14 (35,085,467 to 35,122,532, reverse strand). Ensembl gene ENSG00000092020.
Subcellular location: Nucleus; Cytoplasm
Subcellular location (Human Protein Atlas): Nucleoplasm; Actin filaments; Cytosol; Golgi apparatus; Nuclear bodies; Primary cilium
Gene Ontology:
Molecular function: protein binding
Biological process: B cell homeostasis; positive regulation of B cell differentiation; T cell homeostasis; regulation of dephosphorylation
Cellular component: centrosome; cytoplasm; cytosol; nuclear body; nucleoplasm; nucleus
Genetic constraint (gnomAD): Loss-of-function variants: 27 observed, 38.99 expected, observed/expected ratio (o/e) 0.69, 90% interval 0.51 to 0.95. The upper end of that interval is the gene's LOEUF score, 0.95, which puts it in group 4 of 6, group 1 being the genes least tolerant of losing a copy. Missense variants: 293 observed, 390.43 expected, observed/expected ratio (o/e) 0.75, 90% interval 0.68 to 0.83. Synonymous variants: 139 observed, 135.9 expected, observed/expected ratio (o/e) 1.02, 90% interval 0.89 to 1.18.
Homologues: Orthologues: chimpanzee PPP2R3C (100% identical), macaque PPP2R3C (99% identical), guinea pig PPP2R3C (99% identical), mouse Ppp2r3c (98% identical), pig PPP2R3C (98% identical), dog PPP2R3C (98% identical), rabbit PPP2R3C (98% identical), rat Ppp2r3c (96% identical), zebrafish ppp2r3c (86% identical), tropical clawed frog ppp2r3c (86% identical).
Diseases named in the same sentence as PPP2R3C in open-access papers:
PPP2R3C is named in the same sentence as 13 diseases in open-access papers, as found by Europe PMC text mining. Sharing a sentence is not in itself a finding about the gene and the disease. The quoted sentences say what the papers report.
Autoimmunity (1 paper, 2026). The occurrence of an immune reaction against the organism's own cells or tissues. "Gene therapy restoring PPP2R3C suppresses autoimmunity and lupus nephritis in mice, and its reduction in kidney resident cells indicates a direct renoprotective effect, positioning PPP2R3C as a promising therapeutic target for SLE." (PMID 42298912, 2026).
gonadal dysgenesis (1 paper, 2021). A congenital disorder characterized by the presence of extremely hypoplastic gonads preventing the development of secondary sex characteristics. "This study expands the role of PPP2R3C in the aetiology of gonadal dysgenesis (GD)." (PMID 34714774, 2021).
Intellectual disability (1 paper, 2022). "Apart from PP2A-related intellectual disabilities, some other congenital mutations have been found in PPP2R2B (OMIM#604326) and PPP2R3C (OMIM#618419)." (PMID 36313552, 2022).
lupus nephritis (1 paper, 2026). Glomerulonephritis in the context of systemic lupus erythematosus. "Reduced PPP2R3C expression was also observed in the kidneys of both PIL mice and lupus nephritis patients." (PMID 42298912, 2026).
spinocerebellar ataxia (1 paper, 2022). "In contrast, mutations in PPP2R3C (encoding the regulatory B′′γ or G5PR subunit) were found to be mainly associated with deficits in gonadal development, and mutations in the promotor of PPP2R2B (encoding B55β) with spinocerebellar ataxia." (PMID 36313552, 2022).
cancer (2 papers, 2022 to 2023). A tumor composed of atypical neoplastic, often pleomorphic cells that invade other tissues. "Although a positive role for the PP2A B”α/PR130 subunit (encoded by PPP2R3A) has been inferred in cancer cell migration, the role of the related B”γ/G5PR subunit (encoded by PPP2R3C) in migration or EMT induction remains unclear." (PMID 37170215, 2023).
PPP2R3C also shares sentences with these, for which no sentence is quoted: allergic disease (1 paper); asthma (1); insomnia (1); lupus (1); nasopharyngeal carcinoma (1); Obesity (1); personality disorder (1).